RN7SL592P (RNA, 7SL, cytoplasmic 592, pseudogene)
Gene: Miscellaneous RNA gene on chromosome 9 (2,228,961 to 2,229,241, reverse strand). Ensembl gene ENSG00000264615.
Homologues: Orthologues: chimpanzee Metazoa_SRP (99% identical), macaque Metazoa_SRP (37% identical), macaque Metazoa_SRP (31% identical). Paralogues in human: Metazoa_SRP (71% identical), Metazoa_SRP (68% identical), Metazoa_SRP (67% identical), Metazoa_SRP (66% identical), Metazoa_SRP (65% identical), Metazoa_SRP (64% identical), Metazoa_SRP (61% identical), Metazoa_SRP (59% identical), Metazoa_SRP (58% identical), RN7SL14P (58% identical), Metazoa_SRP (57% identical), RN7SL1 (57% identical), and 700 more.